CARD6 (caspase recruitment domain family member 6)
Description:
May be involved in apoptosis.
Synonyms: CINCIN1
Tractability: PROTAC: ubiquitination databases record sites on it; its protein half-life has been measured.
Gene: Protein-coding gene on chromosome 5 (40,841,308 to 40,860,175, forward strand). Ensembl gene ENSG00000132357.
Gene Ontology:
Molecular function: protein binding
Biological process: regulation of apoptotic process
Cellular component: cytoplasm
Genetic constraint (gnomAD): Loss-of-function variants: 23 observed, 21.9 expected, observed/expected ratio (o/e) 1.05, 90% interval 0.75 to 1.49. The upper end of that interval is the gene's LOEUF score, 1.49, which puts it in group 6 of 6, group 1 being the genes least tolerant of losing a copy. Missense variants: 1,204 observed, 1,263.5 expected, observed/expected ratio (o/e) 0.95, 90% interval 0.91 to 1. Synonymous variants: 397 observed, 455.72 expected, observed/expected ratio (o/e) 0.87, 90% interval 0.8 to 0.95.
Homologues: Orthologues: chimpanzee CARD6 (98% identical), macaque CARD6 (92% identical), dog CARD6 (70% identical), rabbit CARD6 (66% identical), rat Card6 (58% identical), mouse Card6 (58% identical). Paralogues in human: NOL3 (7% identical).
Diseases named in the same sentence as CARD6 in open-access papers:
CARD6 is named in the same sentence as 22 diseases in open-access papers, as found by Europe PMC text mining. Sharing a sentence is not in itself a finding about the gene and the disease. The quoted sentences say what the papers report.
psoriasis (2 papers, 2016 to 2017). An autoimmune condition characterized by red, well-delineated plaques with silvery scales that are usually on the extensor surfaces and scalp. "Although not previously connected to RA, several of these genes were recently shown to be implicated in autoimmunity (e.g. CARD6 in psoriasis, PTGDR in asthma, BPI in cystic fibrosis) and immune-related processes." (PMID 28148290, 2017). "CARD6 has not been linked to psoriasis previously though it was highly upregulated in our PL." (PMID 26976200, 2016).
breast carcinoma (1 paper, 2021). "Claudin domain containing 1 (CLDND1) and Caspase recruitment domain family member 6 (CARD6) were found to regulate the apoptosis in breast cancer and non-alcoholic fatty liver disease, respectively." (PMID 34344298, 2021).
cardiac hypertrophy (1 paper, 2019). "Recently, CARD6 was reported to protect against cardiac hypertrophy in response to pressure overload by regulating mitogen-activated protein kinases (MAPKs) signaling pathway." (PMID 31841440, 2019).
colorectal tumors (1 paper, 2022). "In that study, neoexpression of CARD6 was related to activation of the NF-κB pathway and played a role in the development of esophageal, gastric, and colorectal tumors." (PMID 35055428, 2022).
COVID-19 (1 paper, 2021). A disease caused by infection with severe acute respiratory syndrome coronavirus 2. "SARS-CoV-2-infected PBMC from COVID-19 presented a significantly higher expression of genes related to virus entry (cellular SARS-CoV-2 receptor ACE2) and apoptosis (CARD6, and CARD9); reinforcing CD8+ T cells CD95+ immunophenotyping." (PMID 34571855, 2021).
diabetes (1 paper, 2025). "In the current study, CARD6 mRNA was overexpressed in the T2D group compared to the controls and appeared to be shared between the pGDM and T2D groups, suggesting its role in the pathogenesis of diabetes." (PMID 40868918, 2025).
Hepatic steatosis (1 paper, 2021). Steatosis is a term used to denote lipid accumulation within hepatocytes. "Card6 protects against hepatic steatosis by suppressing Ask1 and is regulated by ENSMUST00000180730.3." (PMID 34368149, 2021).
inflammatory bowel disease (1 paper, 2024). A spectrum of small and large bowel inflammatory diseases of unknown etiology. "CircCARD6 is produced from the CARD6 gene, which encodes an NF-κB activator; this is implicated in inflammatory bowel diseases and gastrointestinal cancers." (PMID 38203852, 2024). "CircCARD6 is generated by the circularisation of exon 3 of the Caspase Recruitment Domain Family Member 6 (CARD6) gene that encodes NF-κB activators, which are implicated in inflammatory bowel diseases and gastrointestinal cancers." (PMID 38203852, 2024).
ischaemic stroke (1 paper, 2022). "Eight hub genes (ADM, ANXA3, CARD6, CPQ, SLC22A4, UBE2S, VIM and ZFP36) were revealed to be significantly correlated with ischaemic stroke by a LASSO logistic regression and SVM-RFE machine learning methods." (PMID 35962388, 2022). "The expression levels of the ADM, ANXA3, CARD6, CPQ, SLC22A4 and VIM genes were significantly increased in the ischaemic stroke patients compared with those in the healthy subjects (p < 0.05–0.01)." (PMID 35962388, 2022). "Eight hub genes (ADM, ANXA3, CARD6, CPQ, SLC22A4, UBE2S, VIM and ZFP36) were revealed to be significantly correlated with ischaemic stroke by the LASSO logistic regression and SVM-RFE algorithm." (PMID 35962388, 2022). "However, the expression levels of the CARD6, CPQ, UBE2S and ZFP36 genes did not significantly differ between the ischaemic stroke patients and normal subjects." (PMID 35962388, 2022).
tumor (3 papers, 2014 to 2023). "Oppositely, upregulation of CARD6 and TNFRSF21 in tumor samples was associated with lower risk of early local recurrence after dCRT." (PMID 34488754, 2021). "The profiling data showed that 7 apoptosis-related genes were concordantly > twofold downregulated in recurrent tumor samples compared with the expression in paired primary tumor samples, including AKT1, BAG4, BCL2A1, BFAR, CARD6, CASP8 and TNFRSF21." (PMID 34488754, 2021). "Furthermore, tumour tissues showed significantly decreased expression of cytoplasmic microbial sensors (NOD1 and NOD2) and downstream signaling molecules for innate microbial sensors such as CARD6, CARD9, and TRAF6 (p = 0.0207, p = 0.0040, and p = 0.0119, respectively)." (PMID 37007104, 2023).
CARD6 also shares sentences with these, for which no sentence is quoted: cancer (3 papers); mastitis (2); asthma (1); Autoimmunity (1); cognitive decline (1); cystic fibrosis (1); gastric cancer (1); leukaemias (1); memory impairment (1); non-alcoholic fatty liver disease (1); ovarian carcinoma (1); squamous carcinoma (1).